MTNAP1 (mitochondrial nucleoid associated protein 1)
Description:
Critical regulator of mitochondrial DNA (mtDNA) abundance. Binds dsDNA throughout the mitochondrial genome without sequence specificity and controls mtDNA copy number by promoting its replication. Also plays important roles in mitochondrial metabolism and cell proliferation.
Synonyms: HLC-8; C17orf80; MIG3; FLJ20721; SPEP1
Tractability: Antibody: UniProt predicts a signal peptide or a membrane-spanning region.
Gene: Protein-coding gene on chromosome 17 (73,232,233 to 73,248,962, forward strand). Ensembl gene ENSG00000141219.
Subcellular location: Mitochondrion inner membrane; Mitochondrion matrix, mitochondrion nucleoid
Subcellular location (Human Protein Atlas): Mitochondria; Cytosol
Gene Ontology:
Molecular function: protein binding
Cellular component: extracellular exosome; mitochondrial inner membrane; mitochondrial nucleoid; mitochondrion
Genetic constraint (gnomAD): Loss-of-function variants: 25 observed, 45.88 expected, observed/expected ratio (o/e) 0.54, 90% interval 0.4 to 0.76. The upper end of that interval is the gene's LOEUF score, 0.76, which puts it in group 3 of 6, group 1 being the genes least tolerant of losing a copy. Missense variants: 757 observed, 728.28 expected, observed/expected ratio (o/e) 1.04, 90% interval 0.98 to 1.1. Synonymous variants: 249 observed, 259.6 expected, observed/expected ratio (o/e) 0.96, 90% interval 0.86 to 1.07.
Homologues: Orthologues: chimpanzee MTNAP1 (98% identical), macaque MTNAP1 (92% identical), dog MTNAP1 (60% identical), pig MTNAP1 (54% identical), rabbit MTNAP1 (54% identical), mouse Mtnap1 (44% identical), rat Mtnap1 (44% identical), guinea pig CUNH17orf80 (12% identical).
Diseases named in the same sentence as MTNAP1 in open-access papers:
MTNAP1 is named in the same sentence as 4 diseases in open-access papers, as found by Europe PMC text mining. Sharing a sentence is not in itself a finding about the gene and the disease.
MTNAP1 shares sentences with these, for which no sentence is quoted: tumor (2 papers); cancer (1); osteosarcoma (1); prostate carcinoma (1).